CXCL6 (C-X-C motif chemokine ligand 6)
Description:
Chemotactic for neutrophil granulocytes. Signals through binding and activation of its receptors (CXCR1 and CXCR2). In addition to its chemotactic and angiogenic properties, it has strong antibacterial activity against Gram-positive and Gram-negative bacteria (90-fold-higher when compared to CXCL5 and CXCL7).
Synonyms: CKA-3; GCP-2; GCP2; SCYB6
Tractability: Antibody: its Gene Ontology location is reachable by antibodies, with high confidence; UniProt places it where antibodies can reach, with medium confidence; UniProt predicts a signal peptide or a membrane-spanning region.
Gene: Protein-coding gene on chromosome 4 (73,836,640 to 73,849,064, forward strand). Ensembl gene ENSG00000124875.
Subcellular location: Secreted
Pathways (Reactome):
Signal Transduction: Chemokine receptors bind chemokines; G alpha (i) signalling events
Gene Ontology:
Molecular function: chemokine activity; protein binding; CXCR chemokine receptor binding
Biological process: antimicrobial humoral immune response mediated by antimicrobial peptide; cellular response to lipopolysaccharide; neutrophil activation; neutrophil chemotaxis; cell-cell signaling; chemotaxis; inflammatory response; signal transduction; antibacterial innate immune response; chemokine-mediated signaling pathway; defense response; immune response
Cellular component: extracellular region
Genetic constraint (gnomAD): Loss-of-function variants: 18 observed, 11.93 expected, observed/expected ratio (o/e) 1.51, 90% interval 1.02 to 1.92. The upper end of that interval is the gene's LOEUF score, 1.92, which puts it in group 6 of 6, group 1 being the genes least tolerant of losing a copy. Missense variants: 171 observed, 153.68 expected, observed/expected ratio (o/e) 1.11, 90% interval 0.98 to 1.26. Synonymous variants: 82 observed, 73.48 expected, observed/expected ratio (o/e) 1.12, 90% interval 0.93 to 1.34.
Homologues: Orthologues: chimpanzee CXCL6 (96% identical), macaque CXCL6 (85% identical), pig AMCF-II (68% identical), guinea pig CXCL6 (60% identical), rat Cxcl6 (60% identical), mouse Cxcl5 (59% identical). Paralogues in human: CXCL5 (80% identical), PPBP (39% identical), CXCL1 (38% identical), CXCL3 (37% identical), CXCL2 (36% identical), PF4 (33% identical), PF4V1 (32% identical), CXCL9 (27% identical), CXCL10 (25% identical), CXCL8 (25% identical), CXCL13 (24% identical), CXCL11 (21% identical).
Diseases named in the same sentence as CXCL6 in open-access papers:
CXCL6 is named in the same sentence as 164 diseases in open-access papers, as found by Europe PMC text mining. Sharing a sentence is not in itself a finding about the gene and the disease. The quoted sentences say what the papers report.
COVID-19 (19 papers, 2020 to 2025). A disease caused by infection with severe acute respiratory syndrome coronavirus 2. "SNPs in the TNF-α, IL-6, IL-8, IL-10, CCL5 and CXCL6 genes have been associated with COVID-19 outcomes and with serum cytokine and chemokine levels." (PMID 40881695, 2025). "The aim of this work was to evaluate the associations of polymorphisms in the TNF-α, IL-6, IL-8, IL-10, CCL5 and CXCL6 genes with COVID-19 outcomes and with the serum levels of IFN-α, IFN-γ, TNF-α, IL-1Ra, IL-6, IL-7, IL-10, CCL2, CCL3, CXCL8, CXCL10 and GCSF." (PMID 40881695, 2025). "Single nucleotide polymorphisms (SNPs) in the TNF-α, IL-6, IL-8, IL-10, CCL5 and CXCL6 genes have been found to be associated with COVID-19 severity, suggesting that SNPs could help explain COVID-19 outcomes." (PMID 40881695, 2025). "However, in our study we did not observe a significant association between rs4279174 of the CXCL6 gene and COVID-19 severity." (PMID 40881695, 2025). "In large airway tissues, genes related to the mucosal layer (MUC4, MUC5AC, MUC5B) as well as cytokine-mediated signaling pathway genes (CCL20, CXCL1, CXCL6, CXCL6, MMP1) and type I interferon genes (IFIT3, ISG15, STAT1, MX1) were upregulated in COVID-19." (PMID 35233546, 2022). "An additional 8 targets (CXCL6, IFI44, IFI44L, RSAD2, S100A8, SPRR2A, SYNE1, XAF1) are associated with COVID-19 pathogenesis, but do not have therapies targeting them available for potential repurposing." (PMID 34582497, 2021). "Consistently, in this study we found the expression of a large number of cytokines are significantly elevated in COVID-19 patients BALF samples compared to control, including pro-inflammatory cytokines CXCL1, CXCL2, CXCL6, CXCL8, CXCL10/IP-10, CCL2/MCP-1, CCL3/MIP-1A and CCL4/MIP1B." (PMID 32228226, 2020). "As notable difference, strong induction of neutrophil-recruiting chemokines targeting CXC chemokine receptor (CXCR) 2, such as CXCL1, CXCL3, CXCL6, and CXCL8, were found only in human basal and secretory cells with severe COVID-19 but were absent in moderately-ill Syrian hamsters." (PMID 34381043, 2021).
hepatocellular carcinoma (17 papers, 2019 to 2025). A malignant tumor that arises from hepatocytes. "In the validation dataset, the results showed that CXCL6, with a p-value of 0.042, was a prognostic factor for hepatocellular carcinoma." (PMID 37325556, 2023). "In a cell-line model of hepatocellular carcinoma, the pineal hormone downregulated CXCL6 at high concentrations." (PMID 32179814, 2020). "Previous study also demonstrated that inhibition of CXCL6 expression restrained the migration and invasion of hepatocellular carcinoma cells." (PMID 30984000, 2019). "The findings corroborate our proposed theory that the induction of the epithelial–mesenchymal transition (EMT) by CXCL6 renders hepatocellular carcinoma (HCC) cells more resistant to radiation." (PMID 37509721, 2023). "In hepatocellular carcinoma (HCC), CLCF1 enhances CXCL6 and TGF-β expression through the Akt/ERK1/2-STAT3 pathway, promoting stem cell traits and self-renewal in cancer cells." (PMID 40969371, 2025). "Previous studies showed that CXCL6 enhances the growth and metastases of ESCC cells both in vitro and in vivo, and the expression of APOH in hepatocellular carcinoma and colorectal cancer was higher than that in adjacent tissues." (PMID 37161430, 2023). "Moreover, studies have suggested that CXCL6 can be regulated by specific cell signaling pathways, such as the HIF-1α pathway in hepatocellular carcinoma and the IL4 pathway through the JAK-STAT mechanism in atopic dermatitis." (PMID 40070583, 2025). "In a recent study on hepatocellular carcinoma (HCC), indirect polarization of TAN to the N2 phenotype was observed by the CAF-induced cytokine factor 1 (CF1), which upregulated the expression of TGF-β and CXCL6 on tumor cells." (PMID 40805183, 2025).
breast carcinoma (15 papers, 2015 to 2025). "Neutrophil infiltration had a direct relationship with the expression of IL1R1, IL1RN, IL1RAP, IL6ST, CXCL3, CXCL5, and CXCL6 in most of the subtypes of the breast cancer patients analyzed." (PMID 39201290, 2024). "CXCL6 stimulates breast cancer development triggering the phosphorylation of ERK1 and ERK2, thus inducing migration and growth of endothelial cells." (PMID 32179814, 2020). "CXCL6 mediates breast cancer progression by pERK1/2-dependent mechanisms and stimulates endothelial cell proliferation and migration." (PMID 31354524, 2019). "Most of the reports in breast cancer bone metastasis evaluating chemokines CXCL6 and CXCL8 focus on CXCR1, expressed by osteoclasts." (PMID 30871004, 2019). "Our previous studies demonstrate that CXCL6/CXCR6 chemokine axis induces prostate cancer progression by the AKT/mTOR signaling pathway; however, its role and mechanisms underlying invasiveness and metastasis of breast cancer are yet to be elucidated." (PMID 25909173, 2015). "This article summarizes existing knowledge about the roles of CXCL ELR-positive chemokines CXCL1, CXCL2, CXCL3, CXCL5, CXCL6, CXCL7, and CXCL8 as peripheral blood and tissue markers in the diagnosis and prognosis of women with breast cancer." (PMID 37370728, 2023). "It has been recently proposed that a FOSL1 signature including TAN-attracting CKs (CXCL8, CXCL6 and CXCL5) is activated in Basal B type breast cancer cell lines." (PMID 31991796, 2020). "The interaction between CXCL6 secreted by breast cancer cells and CXCR6 on naïve MSCs leads to the induction of CXCL10 secretion by MSCs, which in turn acts on CCR3 on breast cancer cells, facilitating the recruitment of MSCs and promoting breast cancer metastasis." (PMID 40676710, 2025). "Additionally, high levels of CXCL1, CXCL3, CXCL5, CXCL6, CXCL7 and CXCL8 are observed in drug-resistant breast cancer cells, which diminishes the effectiveness of other medical interventions." (PMID 31788042, 2019). "However, IL1RN, IL6ST, CXCL3, CXCL5, and CXCL6 gene expression levels were non-significant concerning clinical survival of breast cancer patients according to the Cox proportional Hazard model." (PMID 39201290, 2024). "However, IL1RN, IL6ST, CXCL3, CXCL5, and CXCL6 gene expression levels were non-significant concerning clinical survival of breast cancer patients." (PMID 39201290, 2024). "Additionally, CXCL6 gene expression and ESR1 showed a negative significant (p < 0.05) correlation in breast cancer Her2 and Luminal A patients." (PMID 39201290, 2024).
diabetic nephropathy (10 papers, 2022 to 2024). "The intersection of the two algorithms obtained four key genes for diabetic nephropathy (CXCL6, CD48, C1QB, and COL6A3) which were used to construct the nomogram." (PMID 38028597, 2023). "CXCL6 is highly expressed in diabetic nephropathy, second only to diabetic nephropathy in vasculitis, and approximately the same expression in other kidney diseases." (PMID 38028597, 2023). "In addition to causing renal fibrosis in patients, CXCL6 may also be involved in tubular damage, which explains why the increased CXCL6 expression in our analysis is associated with a deterioration in kidney function in diabetic nephropathy patients." (PMID 38028597, 2023). "CXCL6 also plays an important role in diabetic nephropathy (DN)." (PMID 38168591, 2024). "Although the relevance of CXCL6 has been validated in in vitro using a human podocyte cell line and in kidney biopsies and resections, the role of C3 in remains poorly characterized in kidney tissue from patients with diabetic nephropathy." (PMID 36659918, 2023). "This bioinformatics analysis identified four disulfidptosis-related genes (CXCL6, CD48, C1QB, and COL6A3) with high diagnostic value and their expression may be closely related to the declined renal function in diabetic nephropathy." (PMID 38028597, 2023). "This study identified four key genes (CXCL6, CD48, C1QB, and COL6A3) involved in diabetic nephropathy using a series of bioinformatics methods." (PMID 38028597, 2023). "In the volcano plot, CXCL6, CD48, C1QB, and COL6A3 are all highly expressed in diabetic nephropathy patients, with areas under the ROC curve of 0.908, 0.928, 0.907, and 0.895, respectively." (PMID 38028597, 2023). "CXCL6, a member of the CXC chemokine family, is highly expressed in patients with diabetic nephropathy (DN)." (PMID 36056316, 2022). "Sun’s research found that, in the diabetic nephropathy (DN) model, by activating the JAK/STAT3 signaling pathway, CXCL6 might enhance fibrosis-related variables to hasten the development of DN renal interstitial fibrosis." (PMID 38882664, 2024). "Furthermore, miR-20a was indicated to target CXCL6 and modulate JAK/STAT3 signaling, exerting an inhibitory effect on diabetic nephropathy." (PMID 38216907, 2024). "Thus, monitoring CXCL6, CD48, C1QB, and COL6A3 expression can help in the diagnosis of diabetic nephropathy." (PMID 38028597, 2023). "Likewise, CXCL6 is a potential novel therapeutic target and candidate biomarker for JAK/STAT3 signaling in the treatment of diabetic nephropathy." (PMID 36534664, 2022). "Thus, CXCL6, CD48, C1QB, and COL6A3 may be involved in kidney function deterioration in diabetic nephropathy patients." (PMID 38028597, 2023). "The gradually decreasing glomerular filtration rate and increasing plasma creatinine with the increased expression of CXCL6, CD48, C1QB, and COL6A3 suggests that the deterioration of kidney function in diabetic nephropathy may be closely related to the expression of key genes." (PMID 38028597, 2023). "The expression of CXCL6, CD48, C1QB, and COL6A3 was higher in diabetic nephropathy patients than in normal controls, indicating that their expression is closely related to disease progression, so these key genes may be potential new therapeutic targets for diabetic nephropathy." (PMID 38028597, 2023).
melanoma (10 papers, 2015 to 2025). A malignant, usually aggressive tumor composed of atypical, neoplastic melanocytes. "CXCL6 is known to act as a pro-angiogenic factor and noted to promote the growth and metastasis of various cancers, including melanomas, colon cancer, and lung cancer." (PMID 36975413, 2023). "In this context, the treatment with CXCL6-neutralizing antibodies led to a reduced tumor cell growth and lymphatic metastasis in a melanoma mouse model." (PMID 31963450, 2020). "In another model of melanoma, CXCL6 was shown to be important for neutrophil infiltration into tumor." (PMID 30899263, 2019). "Melanoma cells were transfected to overexpress the GCP-2/CXCL6 chemokine and then implanted into nude mice." (PMID 26819959, 2015). "The new CXCL6-melanoma tumors grew larger and with a well-developed vasculature than wild type (WT) melanomas." (PMID 26819959, 2015). "In a melanoma mouse model, specific anti-CXCL6 monoclonal antibodies reduced the number of TANs and also tumor size." (PMID 26819959, 2015). "Moreover, anti-CXCL6 monoclonal antibodies reduced neutrophil recruitment, which had an effect of inhibiting melanoma growth." (PMID 30899263, 2019). "Notably, CXCL6 exhibited strong negative correlations with B and T cells in primary melanomas, while PGLYRP1 was positively associated with neutrophils and macrophages in metastatic ones." (PMID 40943183, 2025). "Blocking CXCL6 could inhibit the growth and metastases of melanoma." (PMID 37491836, 2023). "The key chemokines involved in TAN recruitment to murine melanoma signal via the CXCR1 and CXCR2 axes, including CXCL1, CXCL2, CXCL6 and CXCL8." (PMID 28435677, 2017).
prostate carcinoma (10 papers, 2015 to 2024). A carcinoma that arises from epithelial cells of the prostate gland. "CXCL6 production is up‐regulated in aged prostate stroma and promotes proliferation of both prostate stromal fibroblasts and epithelium, and increased CXCL6 expression occurs in prostate cancers with high Notch1 levels." (PMID 36608258, 2023). "Chronic hypoxia also increases the expression of CXCL6 in PC-3 prostate cancer cells." (PMID 33467722, 2021). "In turn, cycling hypoxia increases the expression of CXCL6 in PC-3 prostate cancer cells." (PMID 33467722, 2021). "Nagaya and co-workers identified higher expression of the CXC chemokine signaling genes, including CXCL1, CXCL3, CXCL6, CXCR1 and CXCR2 in prostate cancer bone metastases." (PMID 35328625, 2022). "For example, we showed that the expression of CXCL6 and CXCL8, the functional homologs of mouse Cxcl5, are both inversely correlated with that of FOXF2 in human prostate cancer specimens." (PMID 36369237, 2022). "And other study showed that DACH1 repressed CXCL6 and CXCL8 in a dose-dependent manner, and repression required the DS domain in prostate cancer." (PMID 31998654, 2019).
liver fibrosis (9 papers, 2018 to 2024). "In fibrosis patients, increases in CXCL6 levels are present in sera and liver tissue, rendering CXCL6 a possible marker for liver fibrosis." (PMID 38045689, 2023). "Recently, CXCL6 was found to be upregulated in the serum and liver tissue of high-stage liver fibrosis patients and was supposed to participate in fibrogenesis by stimulating Kupffer cells releasing TGF-β and thereby activating stellate cells." (PMID 35111704, 2021). "Confirmatory qRT-PCR analysis showed that the CXCL6 mRNA level was significantly increased in liver tissues from the liver fibrosis group compared with those from the control group." (PMID 34336890, 2021). "More recently, C-X-C Motif Chemokine Ligand 6 (CXCL6) was reported to be involved in liver fibrosis." (PMID 34336890, 2021). "As for the potential role of CXCL6 in liver fibrosis, it has been demonstrated that CXCL6 is involved in the recruitment of monocytes into the liver following liver injury." (PMID 34336890, 2021). "Consistent with these previous studies, we also found that CXCL6 expression is elevated in HBV-induced liver fibrosis." (PMID 34336890, 2021). "This study finds that the expression of SLIT2 and CXCL6 in BA liver is exceptionally high, and it is strongly related to liver fibrosis grade." (PMID 35111704, 2021). "The BRD4 mRNA level was positively correlated with the CXCL6 mRNA level in the hepatic tissues of patients with liver fibrosis." (PMID 34336890, 2021). "It was recently reported that hepatic CXCL6 expression is up-regulated in liver fibrosis and can promote the interaction of BRD4 with other transcriptional factors." (PMID 34336890, 2021). "In this study, patients with various stages of liver fibrosis were analysed and elevated expression of CXCL6 was detected in the sera and liver tissue, with higher expression levels correlating with more advanced stages of the disease." (PMID 30106235, 2018). "Taken together, our results reveal that CXCL6 plays an important role in liver fibrosis through stimulating the release of TGF‐β by KCs and thereby activating HSCs." (PMID 30106235, 2018). "The expression of CXCL6 was found to be elevated in the serum and liver tissue of high stage liver fibrosis patients." (PMID 30106235, 2018). "Notably, CXCL6 plays a pivotal role in liver fibrosis evolution by provoking the release of TGF-β from Kupffer cells (KCs), leading to the activation of the hepatic stellate cell (HSC) line." (PMID 37509721, 2023). "It has been reported that CXCL6 is a prognostic biomarker for liver fibrosis." (PMID 34336890, 2021). "Interestingly, the CXCL6 mRNA level was positively correlated to the BRD4 mRNA level in the liver fibrosis group." (PMID 34336890, 2021). "Notably, a number of previous studies have shown that the CXCL6 level is increased in the sera of patients with liver fibrosis and its expression is increased in the liver tissues of patients with liver fibrosis." (PMID 34336890, 2021). "The elevated expression of CXCL6 in the sera and liver tissue of liver fibrosis patients identified in this study suggests that this chemokine could be an effective marker of liver fibrosis." (PMID 30106235, 2018). "Experiments were then performed to verify the role of CXCL6 in liver fibrosis in vivo." (PMID 30106235, 2018). "The heat map showed that GXF could significantly inhibit the expression of some chemokine-related genes such as CCL2, CXCL6 and CX3CL1, suggesting that GXF may alleviate CCl4-induced liver fibrosis by inhibiting the recruitment of related immune cells." (PMID 35180857, 2022). "Such interactions between CXCL6 and BRD4 might promote the development and progression of liver fibrosis." (PMID 34336890, 2021). "Moreover, the expression of C-X-C motif chemokine ligand 6 (CXCL6), a factor interplayed with BRD4, was increased in hepatic tissues of the patients with liver fibrosis." (PMID 34336890, 2021).